ITPR3 (inositol 1,4,5-trisphosphate receptor type 3)
Description:
Inositol 1,4,5-trisphosphate-gated calcium channel that, upon 1D-myo-inositol 1,4,5-trisphosphate binding, transports calcium from the endoplasmic reticulum lumen to cytoplasm, thus releasing the intracellular calcium and therefore participates in cellular calcium ion homeostasis. 1D-myo-inositol 1,4,5-trisphosphate binds to the ligand-free channel without altering its global conformation, yielding the low-energy resting state, then progresses through resting-to preactivated transitions to the higher energy preactivated state, which increases affinity for calcium, promoting binding of the low basal cytosolic calcium at the juxtamembrane domain (JD) site, favoring the transition through the ensemble of high-energy intermediate states along the trajectory to the fully-open activated state. Upon opening, releases calcium in the cytosol where it can bind to the low-affinity cytoplasmic domain (CD) site and stabilizes the inhibited state to terminate calcium release.
Synonyms: IP3R-3; IP3R3; CMT1J; IMD132; IMD133; IP3R
Tractability: Small molecule: a structure with a bound ligand is known; a high-quality ligand is known; it belongs to a druggable protein family. Antibody: its Gene Ontology location is reachable by antibodies, with high confidence; UniProt predicts a signal peptide or a membrane-spanning region. PROTAC: ubiquitination databases record sites on it; its protein half-life has been measured; a small molecule that binds it is known.
Target class: Ion channel; Ligand-gated ion channel; IP3 receptor
Gene: Protein-coding gene on chromosome 6 (33,620,365 to 33,696,574, forward strand). Ensembl gene ENSG00000096433.
Subcellular location: Endoplasmic reticulum membrane; Cytoplasmic vesicle, secretory vesicle membrane
Subcellular location (Human Protein Atlas): Vesicles; Cytosol
Pathways (Reactome):
Immune System: Antigen activates B Cell Receptor (BCR) leading to generation of second messengers; CLEC7A (Dectin-1) induces NFAT activation; FCERI mediated Ca+2 mobilization; Role of phospholipids in phagocytosis
Signal Transduction: Ca2+ pathway; DAG and IP3 signaling; PLC beta mediated events; VEGFR2 mediated cell proliferation
Hemostasis: Effects of PIP2 hydrolysis; Elevation of cytosolic Ca2+ levels
Metabolism: Glucagon-like Peptide-1 (GLP1) regulates insulin secretion; Regulation of insulin secretion
Disease: FCGR3A-mediated IL10 synthesis
Muscle contraction: Ion homeostasis
Sensory Perception: Sensory perception of sweet, bitter, and umami (glutamate) taste
Gene Ontology:
Molecular function: ATP binding; calcium ion binding; inositol 1,4,5 trisphosphate binding; inositol 1,4,5-trisphosphate-gated calcium channel activity; intracellularly gated calcium channel activity; protein binding; zinc ion binding; inositol 1,3,4,5 tetrakisphosphate binding; inositol hexakisphosphate binding; phosphatidylinositol binding; calcium channel activity; monoatomic ion channel activity
Biological process: calcium ion homeostasis; platelet activation; protein homotetramerization; release of sequestered calcium ion into cytosol; response to calcium ion; G protein-coupled receptor signaling pathway; positive regulation of cytosolic calcium ion concentration; sensory perception of taste; calcium ion transmembrane transport; calcium ion transport; calcium-mediated signaling; monoatomic ion transport; transmembrane transport
Cellular component: endoplasmic reticulum membrane; membrane; plasma membrane; receptor complex; apical part of cell; brush border; cytoplasm; cytoplasmic side of endoplasmic reticulum membrane; endoplasmic reticulum; neuronal cell body; nuclear outer membrane; platelet dense tubular network membrane; sarcoplasmic reticulum; secretory granule membrane; nucleolus; nucleoplasm; nucleus; transport vesicle membrane
Genetic constraint (gnomAD): Loss-of-function variants: 172 observed, 291.11 expected, observed/expected ratio (o/e) 0.59, 90% interval 0.52 to 0.67. The upper end of that interval is the gene's LOEUF score, 0.67, which puts it in group 2 of 6, group 1 being the genes least tolerant of losing a copy. Missense variants: 2,793 observed, 3,668.6 expected, observed/expected ratio (o/e) 0.76, 90% interval 0.74 to 0.79. Synonymous variants: 1,294 observed, 1,471.6 expected, observed/expected ratio (o/e) 0.88, 90% interval 0.84 to 0.92.
Gene-disease validity (ClinGen):
ClinGen rates the evidence that ITPR3 causes each of these diseases.
Charcot-Marie-Tooth disease, demyelinating, type 1J (autosomal dominant): Definitive.
Homologues: Orthologues: macaque ITPR3 (99% identical), chimpanzee ITPR3 (99% identical), pig ITPR3 (97% identical), rat Itpr3 (95% identical), mouse Itpr3 (95% identical), dog ITPR3 (95% identical), guinea pig ITPR3 (95% identical), rabbit ITPR3 (93% identical), tropical clawed frog itpr3 (83% identical), zebrafish itpr3 (74% identical), Caenorhabditis elegans unc-68 (20% identical), Drosophila melanogaster RyR (20% identical). Paralogues in human: ITPR2 (66% identical), ITPR1 (63% identical), RYR1 (24% identical), RYR2 (24% identical), RYR3 (24% identical).
Diseases named in the same sentence as ITPR3 in open-access papers:
ITPR3 is named in the same sentence as 108 diseases in open-access papers, as found by Europe PMC text mining. Sharing a sentence is not in itself a finding about the gene and the disease. The quoted sentences say what the papers report.
breast carcinoma (18 papers, 2010 to 2024). "In a human breast cancer cell line (MCF-7) knockdown of Itpr3 caused cell cycle arrest, supporting that it is important for promoting tumor proliferation." (PMID 28407733, 2017). "ITPR3 encodes an intracellular Ca2+ release channel and is upregulated in actively invading cancer cells and in invasive margin of tumors in colorectal cancer whereas SLC34A2, a sodium/phosphate cotransporter, promotes calcium-phosphate calcifications involved in the development of breast cancer." (PMID 26625260, 2015). "ITPR3, an isoform of the ITPR family, plays a crucial role in the pathogenesis of various diseases, such as alcoholic hepatitis, breast cancer, glioblastoma, gastric cancer." (PMID 39911741, 2024). "Whereas high levels of ITPR3 were observed in the highly migrating and invasive MDA-MB-231 and MDA-MB-435S breast cancer cell lines, the low-migrating MCF-7 showed low levels of ITPR3, but the stable overexpression of ITPR3 increased the migration capacity of this cell line." (PMID 32916960, 2020).
colorectal cancer (12 papers, 2015 to 2024). A primary or metastatic malignant neoplasm that affects the colon or rectum. "An increased expression of ITPR3 has been also observed in cholangiocarcinoma and in colorectal cancer; in both cases the expression of ITPR3 correlated with the degree of neoplasia severity." (PMID 32290556, 2020). "In colorectal cancer DLD-1 cells, the silencing of ITPR3 expression led to a reduction of tumor volumes after injection of these cells in nude mice, increasing the apoptosis of these cells in hypoxic conditions and demonstrating the proliferative and anti-apoptotic role of ITPR3." (PMID 32916960, 2020). "ITPR3 was absent in normal colonic tissue while overexpressed in colorectal cancer." (PMID 35580861, 2022).
glioblastoma (10 papers, 2016 to 2024). The most malignant astrocytic tumor (WHO grade IV). "ITPR3 overexpression is correlated with bad clinic outcomes in cervical squamous cell carcinoma cancer, glioblastoma, cholangiocarcinoma." (PMID 35580861, 2022).
gastric cancer (9 papers, 2010 to 2024). A primary or metastatic malignant neoplasm involving the stomach. "ITPR3 regulates the mobilization of intracellular calcium stores, and the authors conclude that IP3R3 signaling may contribute to peritoneal dissemination of gastric cancer." (PMID 29492218, 2018).
diabetes (7 papers, 2010 to 2025). "The involvement of ITPR3 in diabetes has been also confirmed by the significant recurrence of single nucleotides polymorphisms (SNPs) in the ITPR3 gene in diabetic American women, as well as in a Swedish nationwide study." (PMID 32290556, 2020). "The inositol 1,4,5-triphosphate receptor type 3 (ITPR3) gene plays a critical role in the development of many autoimmune diseases, including Type 1 diabetes mellitus, systemic lupus erythematosus, rheumatoid arthritis, and Grave's disease." (PMID 31614375, 2019). "Both miR-1843b-5p and miR-1224-5p target Atp1a4 and Itpr3, which were connected to cGMP-PKG signaling, another typical pathway impaired in diabetes and obesity." (PMID 32350386, 2020). "Notably, the Ca2+/CAMKII/eNOS/NO signaling axis is a critical pathway for endothelial function, and our findings highlight that reduced ITPR3 expression in diabetic conditions may impair this pathway, leading to diminished CAMKII activation, eNOS phosphorylation, and NO production in diabetes." (PMID 40416809, 2025).
cholangiocarcinoma (6 papers, 2020 to 2023). A carcinoma that arises from the intrahepatic biliary tree (intrahepatic cholangiocarcinoma) or from the junction, or adjacent to the junction, of the right and left hepatic ducts (hilar cholangiocarcinoma). "Similarly, cholangiocarcinoma cells were shown to be particularly sensitive to the knock-out of ITPR3, a genetic manipulation that led to the reduction of cell migration, as well as to the reduction of mitochondrial oxygen consumption and proliferation." (PMID 32916960, 2020).
hepatocellular carcinoma (6 papers, 2020 to 2023). A malignant tumor that arises from hepatocytes. "Overexpression of ITPR3 also participates in the pathogenic mechanism of hepatocellular carcinoma (HCC)." (PMID 35580861, 2022). "Unlike promoter/enhancer demethylation-mediated upregulation of ITPR3, MCM2 and NUP37 in hepatocellular carcinoma." (PMID 36694230, 2023). "In the same line, demethylation of the ITPR3 gene and the ensuing increase in IP3R3 protein levels is also frequent in the development of hepatocellular carcinoma." (PMID 36060801, 2022).
Immunodeficiency (6 papers, 2023 to 2025). Failure of the immune system to protect the body adequately from infection, due to the absence or insufficiency of some component process or substance. "We present the fourth report of ITPR3 mutations causing combined immunodeficiency and further expand the clinical and molecular spectrum of this disorder." (PMID 41019080, 2025). "Recently, two individuals with immunodeficiency were found to carry compound heterozygous variants in ITPR3." (PMID 39804930, 2025). "A de novo variant in the Ca2+ modulator ITPR3 causes a pleiotropic multisystemic disease where immunodeficiency is paramount." (PMID 39270020, 2024). "Defects in IP3R3, caused by mutations in ITPR3 identified in patients with immunodeficiency, were found to impair Ca2+ signaling after T-cell receptor (TCR) stimulation, as presented by Julika Neumann (KU Leuven, Leuven, Belgium)." (PMID 38661208, 2024). "Here, we report that an identical dominant-negative variant in ITPR3 in four independent families from France, Israel, and the United States is causative of a complex syndromic immunodeficiency with variable multisystemic manifestations." (PMID 39270020, 2024). "Here, we provide evidence showing that inherited variants in ITPR3 alter physiologically relevant Ca2+ signaling responses, driving defects in immune responses, and are associated with clinical immunodeficiency." (PMID 36302985, 2023). "In this study, we identified two unrelated patients with immunodeficiency and immune dysregulation who harbored compound heterozygous ITPR3 variants." (PMID 36302985, 2023). "The identification of new patients in subsequent studies will be highly informative for identifying the mutational space in ITPR3 associated with immunodeficiency." (PMID 36302985, 2023). "In this study, we identified compound heterozygous variants of ITPR3 (a gene encoding IP3R subtype 3) in two unrelated Caucasian patients presenting with immunodeficiency." (PMID 36302985, 2023). "With this study, we add variants in ITPR3 as underlying causes for disrupted Ca2+ signaling that results in immunodeficiency." (PMID 36302985, 2023). "Subsequent reports have identified monoallelic dominant-negative ITPR3 mutations in patients with CID and multisystem involvement, expanding the spectrum of Ca2+ signaling-related immunodeficiencies." (PMID 41019080, 2025). "ITPR3 belongs to an intriguing class of immunodeficiency genes involved in common cellular pathways." (PMID 36302985, 2023). "The identification of ITPR3-related immune dysregulation further diversifies the spectrum of calcium-related immune disorders and has, besides further understanding of calcium homeostasis and the function of the immune system, obvious etiological, diagnostic, nosological, and therapeutic relevance." (PMID 39270020, 2024). "Notably, ITPR3 has previously been implicated in autosomal dominant Charcot-Marie-Tooth disease, although severe immunodeficiency was not described in these patients." (PMID 41019080, 2025).
colon cancer (5 papers, 2017 to 2023). "For instance, in colon cancer, greater ITPR3 expression is associated with cancer cell proliferation and lower 5-year survival of patients." (PMID 32916960, 2020). "In colon cancer, increased ITPR3 expression is related to increased metastasis and decreased patient survival, and increased ITPR3 can lead to reduced apoptosis or vice versa." (PMID 33573671, 2021). "On the other hand, ITPR3 knock-down in Caco-2 colon cancer cells enhances apoptosis, while over-expression enhances cell survival." (PMID 32916960, 2020). "In addition, a few studies found that overexpression of ITPR3 in breast and colon cancer cells decreased apoptosis, while knockdown of the receptor enhanced apoptosis." (PMID 28036301, 2017).
prostate carcinoma (5 papers, 2017 to 2023). A carcinoma that arises from epithelial cells of the prostate gland. "Downregulation of IP3R3 (inositol 1,4,5-trisphosphate receptor type 3) has been proposed to be oncogenic by promoting proapoptotic mitochondrial Ca2+ transfer in breast and prostate cancer." (PMID 36588538, 2022). "While in prostate cancer, ITPR3 can limit tumor growth by regulating Ca2 + −dependent apoptosis, in which the more ITPR3 is degraded, the less apoptosis occurs." (PMID 33573671, 2021).
rheumatoid arthritis (5 papers, 2014 to 2021). A chronic, systemic autoimmune disorder characterized by inflammation in the synovial membranes and articular surfaces. "For the co-morbidities, the most significant association was noted between ITPR3 and rheumatoid arthritis (p = 4.88E−38)." (PMID 31628418, 2021). "Moreover, genetic studies have shown that the SNPs of ITPR3 are closely associated with T1D in Caucasian populations and autoimmune diseases (namely, systemic lupus erythematosus, rheumatoid arthritis, and Graves’ disease) in Japanese populations." (PMID 35046894, 2021). "Moreover, rs3748079, a SNP located in the promoter region of ITPR3, has been associated with several autoimmune diseases including systemic lupus erythematosus, rheumatoid arthritis, and Graves’ disease in a Japanese population, and the variant rs999943 of ITPR3 has been linked to obesity." (PMID 32290556, 2020). "As revealed by another GWAS, the involvement of ITPR3 in the release of the macrophage migration inhibitory factor (MIF) confirmed the role of this receptor in rheumatoid arthritis." (PMID 32290556, 2020).
type 1 diabetes (5 papers, 2012 to 2022). "The major genetic influences for type 1 diabetes have been mapped on human chromosome 6 in a locus containing MHC class II genes and the ITPR3 gene, but other genes in or near this locus have been suspected to contribute to type 1 diabetes risk." (PMID 22363741, 2012). "Interestingly, the ITPR3 gene has been associated to type 1 diabetes, which curiously shows a correlation with risk of ADHD in the offspring." (PMID 35013130, 2022).
lung cancer (4 papers, 2021 to 2025). A malignant neoplasm involving the lung. "Additionally, ITPR3 variants are associated with better survival outcomes in non–small cell lung cancer, suggesting a broader role in lung pathology." (PMID 40045538, 2025). "Moreover, the high ITPR3 expression in lung cancer was associated with a better prognosis." (PMID 36588538, 2022). "We first assessed associations between the expression values of all ITPRs (ITPR1, ITPR2, ITPR3) and overall survival in lung cancer patients." (PMID 35625784, 2022). "In keeping with the fact that lung cancer cells have more complex genetic landscapes than SCCOHT15,62, only four genes, namely ITPR3, MATN2, EHD4, and ATP2B4, were consistently upregulated by SMARCA4 in both cancer types." (PMID 34518526, 2021). "To further validate our findings of ITPR3 regulation by SMARCA4/2 in cell models with genetic perturbation, we analyzed mRNA expression of ITPR3 and SMARCA4/2 in RNA-seq data sets of ovarian (n = 47) and lung cancer (n = 192) cell lines available from CCLE41,42." (PMID 34518526, 2021).
alcoholic hepatitis (3 papers, 2018 to 2025). Acute hepatitis resulting from ingestion of alcohol. "The expression of ITPR3 is decreased in cholangiocytes from patients with sclerosing cholangitis, primary biliary cholangitis, benign or malignant biliary obstruction, biliary atresia, sepsis, and alcoholic hepatitis." (PMID 30563259, 2018).
asthma (3 papers, 2021 to 2023). "Targets located in the MHC locus (NOTCH4 and ITPR3) were associated with 41 different phenotypes, including ulcerative colitis and multiple sclerosis signals in the opposite direction from asthma." (PMID 34103634, 2021). "The study found that three shared genes i.e ITPR3, HEXIM1, and IQCH were involved between insomnia and asthma, while ITPR3 and HEXIM1 seem to be associated with an inflammatory response." (PMID 37163444, 2023). "Among the shared genes, three genes, ITPR3, HEXIM1, and IQCH, were found to be reported in both GWASs of asthma and insomnia, and two genes, ITPR3 and HEXIM1 appear to be involved in the inflammation process." (PMID 34750467, 2021).
autoimmune disease (3 papers, 2019 to 2021). A disorder resulting from loss of function or tissue destruction of an organ or multiple organs, arising from humoral or cellular immune responses of the individual to their own tissue constituents. "Upregulation of ITPR3 expression may induce autoimmune disorders and promote the occurrence and development of T1D by activating T cells." (PMID 35046894, 2021).
cholestasis (3 papers, 2018 to 2025). Impairment of the bile flow caused by obstruction within the liver, or outside the liver in the bile duct system. "Specific knockdown of ITPR3 in cholangiocytes is sufficient to impair ductular HCO3− secretion, which suggests that the loss of ITPR3 in human disorders contributes to cholestasis." (PMID 30563259, 2018). "Expression of ITPR3 is reduced in many cholestatic diseases such as bile duct obstruction, biliary atresia, primary biliary cholangitis, and primary sclerosing cholangitis, resulting in diminished calcium signaling and calcium-mediated bicarbonate secretion." (PMID 30023358, 2018). "Importantly, downregulation of ITPR3 is specific to cholestatic conditions, as it is not seen in hepatitis C viral infection, which is associated with inflammation but not cholestasis per se." (PMID 30023358, 2018).
mesothelioma (3 papers, 2015 to 2023). A usually malignant and aggressive neoplasm of the mesothelium which is often associated with exposure to asbestos. "Several investigators have reported that the loss of ITPR3 can impair mitochondrial calcium signaling and reduce apoptosis, thus leading to premalignant conditions in various cancers, such as melanoma and mesothelioma." (PMID 33573671, 2021). "Thus, we investigated the possible relationship between ITPR3 and AKT in mesothelioma cells." (PMID 26156019, 2015).